YAP1 (Yes1 associated transcriptional regulator)
Diseases named in the same sentence as YAP1 in open-access papers (continued):
Sharing a sentence is not in itself a finding about the gene and the disease.
COVID-19 (2 papers, 2021 to 2022). A disease caused by infection with severe acute respiratory syndrome coronavirus 2. "Additionally, YAP1 can serve as a node connecting inflammation and the N6-methyladenosine (m6A) modification system in COVID-19-associated ARDS." (PMID 35409008, 2022). "YAP1 also gets upregulated in COVID-19 patients BALF and SARS-CoV-2 infection in liver organoids (GSE151803)." (PMID 34407143, 2021).
hypertrophic cardiomyopathy (2 papers, 2024 to 2025). A condition in which the myocardium is hypertrophied without an obvious cause. "YAP1 knockout mediates the development of DCM, while hypertrophic cardiomyopathy (HCM) involves a deficiency in Hippo signaling, the upregulation of YAP1 transcript and protein levels, as well as the downregulation of its Ser127 phosphorylation." (PMID 38539233, 2024). "Given that fibrosis is a common feature in both ischemic and hypertrophic cardiomyopathy, the interaction of NAP1L1 with pathways regulating cardiac remodeling, such as YAP1, may be relevant." (PMID 40169585, 2025).
immune deficient (2 papers, 2019 to 2023). "Activation of YAP1 in the cervical epithelium leads to congenital antiviral immunodeficiency, causing persistent HPV infection." (PMID 32038526, 2019). "However, we show that YAP1 has both chromosomal loss and downregulated expression in the aggressive subgroup of immune deficient MPNSTs with a high frequency of loss and LOH." (PMID 37837931, 2023).
injury (2 papers, 2022 to 2024). Damage inflicted on the body as the direct or indirect result of an external force, with or without disruption of structural continuity. "Conversely, YAP1 was found to be suppressed in tubule cells from adriamycin-induced kidney injury mice model, and preserved YAP1 plays a crucial role in mediating tubule cell regeneration during kidney recovery." (PMID 39608245, 2024). "Moreover, our study also showed that YAP1 promoted the expression of SLC7A11 and increased the GPX4 and GSH level both in septic liver injury mice and LPS-stimulated LO2 cells, while suppressed the expression of ACSL4." (PMID 36182901, 2022). "Although growing evidence indicated that ferroptosis played a role in the genesis and progression of septic liver injury, there was no report about YAP1 function on ferroptosis in septic liver injury." (PMID 36182901, 2022).
invasive lobular carcinoma (2 papers, 2016 to 2021). "Previously, studies found that invasive lobular carcinoma was characterized by a high expression of nuclear Yap1." (PMID 26695440, 2016).
lung diseases (2 papers, 2019 to 2022). "Consequently, one of the future challenges toward the application of YAP1 in lung diseases is activating YAP1 precisely without inducing cancer." (PMID 35979359, 2022).
male infertility (2 papers, 2024 to 2025). The inability of the male to effect fertilization of an ovum after a specified period of unprotected intercourse. "Collectively, we are the first to demonstrate that the YAP1/RAD21/NEDD4 pathway mediates the fate determinations of human SSCs and abnormality or mutations of YAP1 are associated with male infertility." (PMID 39659446, 2024). "Collectively, these results highlight a critical role of YAP1 in determining the fate determinations of human SSCs and male infertility through the YAP1/RAD21/NEDD4 pathway." (PMID 39659446, 2024). "Double deficiency of Mst1 and Mst2, upstream effectors of YAP1, has been observed in male infertility, and the Hippo pathway may affect male reproduction development, except for YAP1, MST1, and MST2." (PMID 39659446, 2024).
malignant pleural mesothelioma (2 papers, 2017 to 2022). A malignant neoplasm that arises from mesothelial cells in the pleura and shows a diffuse growth pattern. "Malignant pleural mesothelioma, a tumor arising from the membrane covering the lungs and the inner side of the ribs, is a cancer in which genetic alterations of genes encoding proteins that act on or are part of the Hippo-YAP1 signaling pathway are frequent." (PMID 35689194, 2022). "Our data demonstrate that, in the context of a Hippo pathway mutated background, YAP1 activity alone is enough to maintain the growth of established tumors in vivo, thus validating the concept of inhibiting the activated YAP1-TEAD complex for the treatment of malignant pleural mesothelioma patients." (PMID 35689194, 2022).
metastatic cancer (2 papers, 2021 to 2023). A carcinoma which has spread from the original site of growth to another anatomic site. "On the other hand, it has been demonstrated that in EMT or metastatic cancer cells, the activation of YAP1 will up-regulate a variety of irons including acyl-CoA synthase long-chain family member 4 (ACSL 4) and transferrin receptor." (PMID 33996543, 2021).
migraine (2 papers, 2022 to 2023). "Of note, hsa-miR-605-3p targets COL4A1, PNKD, TGFBR2, and YAP1, which have been identified as susceptible genes in migraine patients." (PMID 36704329, 2022). "miR-550a-3-5p specifically targeted YAP1, and YAP1 was one of the migraine susceptibility genes." (PMID 36704329, 2022). "Apart from YAP1, all of these genes had strong evidence of being co-localised (PP4 > 0.5) with a migraine index SNP." (PMID 37245199, 2023).
neuroendocrine neoplasm (2 papers, 2022 to 2023). Endocrine tumors, also referred to as neuroendocrine tumors (NETs), are defined by a common phenotype which is characterized by the expression of general markers (neuron specific enolase, chromogranin, synaptophysin) and hormone secretion products. "Insight into the contribution of YAP1 guided the evaluation of combinations of HDAC and NAMPT inhibitors for the treatment of neuroendocrine neoplasms." (PMID 37894327, 2023). "Unlike other neuroendocrine tumors (such as MCT), what emerged from our data is that the Hippo pathway may have an oncogenic role in Pheo, judging from the overexpression of YAP1 and TNKS1." (PMID 35269556, 2022).
Neurofibromatosis type 2 (2 papers, 2024 to 2025). "Neurofibromatosis type 2, now termed NF2-related schwannomatosis, caused by a mutation in the NF2 gene, results in the loss of function of Merlin, a tumor suppressor protein, which leads to the overexpression of YAP1 (yes-associated protein 1)." (PMID 39202270, 2024).
oligodendroglioma (2 papers, 2022 to 2025). A well-differentiated (WHO grade II), diffusely infiltrating neuroglial tumor, typically located in the cerebral hemispheres. "Interestingly, in the case containing areas of conventional oligodendroglioma the YAP1 expression was strictly confined to the sarcomatous part of the tumor (online resource)." (PMID 34967922, 2022). "YAP1 was strongly and widely positive in the cytoplasm and nucleus of tumor cells in 10/11 (91%) oligosarcomas, while only 1 out of 20 (5%) conventional oligodendrogliomas showed YAP1 staining, with only a subset of tumor cells being positive." (PMID 34967922, 2022).
parathyroid adenomas (2 papers, 2021). "In the series of parathyroid adenomas, coexpression of YAP1 and CASR was analyzed by immunohistochemistry (IHC)." (PMID 33670622, 2021). "Compared with normal parathyroid glands, parathyroid adenomas (PAds) and carcinomas show variably but reduced nuclear YAP1 expression." (PMID 33670622, 2021). "Considering that both CASR and YAP1 feature as tumor suppressors in parathyroid adenomas, the induction of SOX2 expression may promote cell resting more than cell proliferation." (PMID 34199594, 2021). "Therefore, in parathyroid adenomas, downregulated CASR-related proteins are associated with low YAP1 nuclear accumulation and, likely, activity." (PMID 33670622, 2021). "The expression of the Hippo cofactor YAP1 was investigated by immunohistochemistry in formalin-fixed paraffin-embedded (FFPE) sections from normal parathyroid glands (PaNs, n = 4), parathyroid adenomas (PAds, n = 11), and parathyroid carcinomas (PCas, n = 6)." (PMID 33670622, 2021).
Parathyroid Tumors (2 papers, 2021). "Here, we investigated the Hippo coactivator Yes-associated protein 1 (YAP1) and the kinase large tumor suppressor 1/2 (LATS1/2) in tumors of the parathyroid glands, which are almost invariably associated with primary hyperparathyroidism." (PMID 33670622, 2021). "The YAP1 expression pattern detected in parathyroid tumors reflects the heterogeneous expression of the CASR protein, which has been extensively reported in previous studies." (PMID 33670622, 2021). "The YAP1 variable downregulation observed in parathyroid tumor tissues resembles the extensively described heterogeneous expression of CASR in these tumors." (PMID 33670622, 2021). "In line with our hypothesis, parathyroid tumor cells with an intense CASR staining showed YAP1 nuclear expression." (PMID 33670622, 2021). "In conclusion, we investigated the Hippo/YAP1 pathway in parathyroid tumors." (PMID 33670622, 2021). "Filamin A binds to and promotes activation of RhoA; therefore, filamin A and Gαq/11 downregulation occurring in parathyroid tumors may inhibit RhoA activation and the inhibitory effect of the Hippo signaling pathway on YAP1, contributing to reduction in YAP1 nuclear accumulation." (PMID 33670622, 2021). "Data suggest that YAP1 may act as an oncosuppressor in parathyroid tumor cells." (PMID 33670622, 2021). "Here, we first report that the Hippo signaling cofactor YAP1 and the upstream components LATS1/2 are expressed and deregulated in parathyroid tumors." (PMID 33670622, 2021). "We propose a tumor suppressor role for YAP1 and LATS1/2 in parathyroid tumors." (PMID 33670622, 2021). "Indeed, we detected a great variability in the number of cells with YAP1 positive nuclear immunostaining, and these findings are likely related to the variable downregulation of the CASR in parathyroid tumors." (PMID 33670622, 2021). "Therefore, YAP1 and MEN1 mutually and differently regulated their expression levels, suggesting that genetic and epigenetic aberrations occurring in parathyroid tumors may determine the degree of activity of the two genes and their target genes." (PMID 33670622, 2021).
pilocytic astrocytoma (2 papers, 2023). Pilocytic astrocytoma is a rare subtype of low-grade glioma of the central nervous system characterized by a well circumscribed, often cystic, brain tumor with a discrete mural nodule and long, hair-like projections that extend from the neoplastic astrocytes. "We also examined more tumor‐related markers in PDOs at day 28, such as YAP1 and p75 NGFR for SHH MB and synaptophysin for pilocytic astrocytoma (Fig EV3E–H)." (PMID 38037472, 2023).
preeclampsia (2 papers, 2020 to 2021). Preeclampsia is a hypertensive disorder of pregnancy that is characterized by new-onset hypertension with proteinuria presenting after 20 weeks of gestation, and depending on mild or severe forms may initially present with severe headache, visual disturbances, and hyperreflexia. "Several reports have demonstrated that RUNX1 and YAP1 have active roles in preeclampsia, but these genes might be novel target for GDM." (PMID 33890634, 2021).
promyelocytic leukemia (2 papers, 2015 to 2021). "Meanwhile, YAP1 has ever been defined as a tumor suppressor that induces apoptosis in response to DNA damage in collaboration with p73 and promyelocytic leukemia in a few cancers." (PMID 26263504, 2015). "In promyelocytic leukemia, YAP1 was further shown to induces apoptosis in response to DNA damage, indicating that YAP might play a role in tumor suppression." (PMID 34257617, 2021).
rectal adenocarcinoma (2 papers, 2017 to 2022). "Our tissue microarray analysis supported that YAP1 expression was found in normal colon crypts and a significantly increased signal was identified in the rectal adenocarcinoma section." (PMID 28241877, 2017).
retinoblastoma (2 papers, 2022 to 2023). A malignant tumor that originates in the nuclear layer of the retina. "LINC00152 enhanced the aggressiveness of retinoblastoma and boosted carboplatin and Adriamycin resistance by regulating YAP1 by sponging miR-613 in human retinoblastoma." (PMID 36033524, 2022). "LINC00152 regulates the expression of YAP1 in retinoblastoma cells by sponging miR-613, and knockdown of YAP1 eliminates the miR-613-mediated effects on retinoblastoma cell proliferation, invasion, apoptosis, autophagy, and chemical resistance." (PMID 36033524, 2022). "In human retinoblastoma (RB), LINC00152 was reported to boost DOX resistance by sponging miR-613 to positively regulate YAP1." (PMID 37781691, 2023).
seminoma (2 papers, 2016 to 2022). A radiosensitive malignant germ cell tumor found in the testis (especially undescended), and extragonadal sites (anterior mediastinum and pineal gland). "According these results, both seminoma and non-seminoma tissues had higher expression levels of YAP1 than the adjacent testicular tissues (Ad)." (PMID 35264157, 2022). "Our qPCR results also confirmed that the YAP1 levels were higher in the non-seminoma NTERA-2 cells than in the seminoma TCam-2 cells." (PMID 35264157, 2022). "Thus, we assessed the expression level of YAP1 in seminoma and non-seminoma cells and found that it played an important role in the cell cycle of TGCTs." (PMID 35264157, 2022). "However, the expression level of YAP1 in seminomas and non-seminomas is still unclear." (PMID 35264157, 2022). "Compared with the non-seminomas, a lower expression level of YAP1 was detected in seminomas than the non-seminomas ones." (PMID 35264157, 2022). "In our study, we first compared YAP1 expression between seminoma and non-seminoma and found that the expression of YAP1 in NTERA-2 cells was significantly higher than that in seminoma cells, which is consistent with the TCGA database results." (PMID 35264157, 2022). "Our data revealed that YAP1/CDK6/CDK4/cyclinD1/RB could be a potential therapeutic axis in TGCTs and sequential regimens of metformin and cisplatin could be a useful therapy for human seminomas and non-seminomas." (PMID 35264157, 2022).
steatosis (2 papers, 2018 to 2019). Increased lipid within the cytoplasm of cells. "In addition, miR-375 suppresses malignant phenotypes of HCC by targeting Astrocyte elevated gene-1 (AEG-1) and Yes-associated protein 1 (YAP1) which mediate steatosis and hepatic proliferation/differentiation respectively." (PMID 30544653, 2018). "Furthermore, histological steatosis was pronounced upon Yap1 knockdown, consistent with the macroscopic liver appearance." (PMID 30740593, 2019).
testicular germ cell tumor (2 papers, 2021 to 2022). A germ cell tumor arising from the testis. "The “TCGA Testicular Germ Cell Tumors (TGCT)” dataset (118 samples) was selected, and the following terms were queried using the ‘Search’ box: YAP1; JNK_pT183Y185; AKT_pT308." (PMID 33643710, 2021).
Thrombocytosis (2 papers, 2017 to 2020). Increased numbers of platelets in the peripheral blood. "Reduction of YAP1 in cancer cells in vivo protects against thrombocytosis-induced increase in metastasis." (PMID 28827520, 2017). "The importance of YAP1 in this context has been confirmed in vivo, as a reduction of YAP1 in cancer cells could protect against a thrombocytosis-induced increase in metastasis." (PMID 32244723, 2020).
undifferentiated pleomorphic sarcoma (2 papers, 2019 to 2025). An undifferentiated soft tissue sarcoma characterized by the presence of a pleomorphic malignant cellular infiltrate. "In undifferentiated pleomorphic sarcoma (UPS), the oncogenic driver yes-associated protein 1 (YAP1) was found to promote matrix remodeling, specifically through increasing the deposition of α3(VI) into the extracellular matrix." (PMID 41228242, 2025).
Ureteral obstruction (2 papers, 2020 to 2023). Obstruction of the flow of urine through the ureter. "The involvement of LOX, not only as a target, but as a modulator of YAP1, was reported in unilateral ureteral obstruction, where upregulation of the ERK/YAP1/Kfl5/cyclin D axis was suppressed by LOX inhibition." (PMID 32708046, 2020).
acute respiratory distress syndrome (1 paper, 2024). Progressive and life-threatening pulmonary distress in the absence of an underlying pulmonary condition, usually following major trauma or surgery. "Previous studies have reported that YAP1 expression is dysregulated in endothelial cells of ARDS (acute respiratory distress syndrome) and that YAP1 overexpression protects against endothelial damage caused by LPS." (PMID 38840498, 2024).
adenovirus infection (1 paper, 2023). "To further explore whether USP15 mediated hPASMC proliferation and migration in a YAP1/TAZ-dependent manner, we achieved the depletion of YAP1 or TAZ in USP15-overexpressing hPASMCs by corresponding adenovirus infection." (PMID 36635430, 2023).
adnexal skin tumors (1 paper, 2022). "A study of six cases of adnexal skin tumors identified YAP1 gene fusion." (PMID 36358649, 2022).
AIDS (1 paper, 2023). A syndrome resulting from the acquired deficiency of cellular immunity caused by the human immunodeficiency virus (HIV).
aneurysm (1 paper, 2024). Bulging or ballooning in an area of an artery secondary to arterial wall weakening. "Meanwhile, we compared human AAA tissues to normal blood vessel tissues near aneurysms with western blotting test also showed that YAP1 expression was increased in AAA." (PMID 39495769, 2024). "The role of YAP1 in aneurysm has not been elucidated clearly." (PMID 39495769, 2024). "In order to determine whether YAP1 participates in the formation of AAA, we applied YAP1 inhibitor‐Verteporfin to block the function of YAP1 in the elastase‐induced and CaCl2‐induced AAA model, and observed the abdominal aortic dilation and aneurysm formation rate." (PMID 39495769, 2024).
ankylosis (1 paper, 2024). Fixation and immobility of a joint. "In this study, Ang2, TIE2 and Yap1 are in the increased expression group, which indicates that ankylosis formation may be dominated by the Ang proteins and activated by the Hippo signaling pathway." (PMID 38418977, 2024).
aortic aneurysm (1 paper, 2023). A ruptured aneurysm located in the wall of the proximal portion of the descending aorta proceeding from the arch of the aorta. "Here, we identified reduced expression of YAP1 in human aortic aneurysms." (PMID 37561588, 2023).
Aortic dissection (1 paper, 2019). Aortic dissection refers to a tear in the intimal layer of the aorta causing a separation between the intima and the medial layers of the aorta. "Many genes, such as YAP1, Sirtuin-1, PCSK9, polycystin-1, and brahma-related gene 1, have also been reported to be associated with the pathophysiologic processes of aortic dissection by influencing the proliferation and migration of VSMCs." (PMID 31751374, 2019).
artery disease (1 paper, 2023). "Researchers found CFDP1 (along with YAP1 and STAT6) for HCAECs that passed the 5% false discovery level (FDR) correction at the gene level which associates CFDP1 with artery disease traits." (PMID 37566073, 2023).
ascending aortic aneurysms (1 paper, 2024). "It is suggested that YAP1 expression reduced in patients with ascending aortic aneurysms and VSMCs, which was associated with VSMCs apoptosis and extracellular matrix (ECM) disorders of the media." (PMID 39495769, 2024).
Asperger’s syndrome (1 paper, 2017). "However, the p.Asn387Thrfs*16 frameshift reported here is located within exon 7 of YAP1 and is predicted to affect all known splice forms, yet with the exception of Asperger’s syndrome the patient has no extraocular phenotype." (PMID 28801591, 2017).